RNU2-42P (RNA, U2 small nuclear 42, pseudogene)
Gene: Small nuclear RNA gene on chromosome 10 (125,890,566 to 125,890,678, reverse strand). Ensembl gene ENSG00000222629.
Homologues: Orthologues: chimpanzee U2 (100% identical), macaque U2 (67% identical), guinea pig U2 (59% identical), dog U2 (58% identical), guinea pig U2 (58% identical), mouse Gm23788 (54% identical), pig U2 (53% identical), guinea pig U2 (52% identical), tropical clawed frog U2 (50% identical), dog U2 (48% identical), tropical clawed frog U2 (44% identical), rabbit U2 (42% identical). Paralogues in human: U2 (99% identical), RNU2-29P (59% identical), RNU2-34P (58% identical), RNU2-41P (58% identical), RNU2-22P (58% identical), RNU2-53P (57% identical), RNU2-2 (56% identical), U2 (56% identical), RNU2-28P (55% identical), RNU2-4P (55% identical), RNU2-59P (55% identical), RNU2-6P (55% identical), and 63 more.